UBIAD1 (UbiA prenyltransferase domain containing 1)
Diseases named in the same sentence as UBIAD1 in open-access papers (continued):
Sharing a sentence is not in itself a finding about the gene and the disease.
UBIAD1 also shares sentences with these, for which no sentence is quoted: anemia (2 papers); Parkinson disease (2); posterior polymorphous corneal dystrophy (2); transitional cell carcinoma (2); adenovirus infection (1); bladder transitional cell carcinoma (1); bladder tumor (1); Blindness (1); breast tumours (1); chordoma (1); congenital stromal corneal dystrophy (1); connective tissue diseases (1); corneal disorder (1); Corneal opacity (1); cutaneous melanoma (1); dyslipidemia (1); fleck corneal dystrophy (1); Fuchs endothelial corneal dystrophy (1); gelatinous drop-like corneal dystrophy (1); granular corneal dystrophy type II (1); lattice corneal dystrophy (1); LCAT deficiency (1); metastatic cancer (1); microphthalmia (1); neuroblastoma (1); posterior polymorphous corneal dystrophy 3 (1); Reis-Bücklers corneal dystrophy (1); renal cell carcinoma (1); renal clear cell cancers (1); renal disease (1).
A further 1 disease shares a sentence with UBIAD1 in 1 paper.